CCND1 (cyclin D1)
Diseases named in the same sentence as CCND1 in open-access papers (continued):
Sharing a sentence is not in itself a finding about the gene and the disease.
Ewing sarcoma (18 papers, 2012 to 2026). A small round cell tumor that lacks morphologic, immunohistochemical, and electron microscopic evidence of neuroectodermal differentiation. "OX40L transgenic Ewing sarcoma cells showed preserved expression of Ewing sarcoma-associated (anti)gens including lipase member I, cyclin D1 (CCND1), cytochrome P450 family member 26B1 (CYP26B1), and the Ewing sarcoma breakpoint region 1-friend leukemia virus integration 1 (EWSR1-FLI1) oncogene." (PMID 26579494, 2015). "In this study, we identified and validated etoposide as a regulator of pncCCND1_B expression and activity on the CCND1 promoter in Ewing sarcoma cells." (PMID 35326688, 2022). "In this study, we investigated the regulation of CCND1 expression in Ewing sarcoma cells upon exposure to chemotherapeutic drugs." (PMID 35326688, 2022). "A similar regulation was also observed in SK-N-MC Ewing sarcoma cells, which express lower levels of Cyclin D1 than TC-71 cells, suggesting a general effect in Ewing sarcoma." (PMID 35326688, 2022). "PncCCND1_B is driven by the promoter region of CCND1 and regulates CCND1 expression in Ewing sarcoma through recruitment of a multi-molecular complex composed of the RNA binding protein Sam68 and the DNA/RNA helicase DHX9." (PMID 35326688, 2022). "In the search for factors that regulate CCND1 expression in Ewing sarcoma cells, Palombo-R and colleagues discovered that the lncRNA pncCCND1_B is transcribed from the CCND1 promoter region." (PMID 35455947, 2022). "In this work, we found that exposure to etoposide, a topoisomerase II inhibitor usually administered in combination with other drugs in the standard regimen for Ewing sarcoma treatment, induced cell death and reduced CCND1 levels." (PMID 35326688, 2022). "Pan-inhibitor screening indicated that etoposide, a drug used for Ewing sarcoma treatment, promotes transcription of pncCCND1_B and repression of CCND1 expression." (PMID 35326688, 2022). "Collectively, these experiments show that etoposide treatment induces upregulation of pncCCND1_B and downregulation of CCND1 in Ewing sarcoma cells." (PMID 35326688, 2022). "By binding to the RNA helicase DHX9, EWS-FLI1 promotes the transcription of oncogenes involved in Ewing sarcoma progression, including cyclin D1." (PMID 32722129, 2020). "The interaction between Sam68 and pncCCND1_B is a key molecular event driving cyclin D1 repression in Ewing sarcoma." (PMID 32722129, 2020). "PncCCND1_B is the prominent CCND1 pancRNA in Ewing sarcoma, one of the most aggressive pediatric cancers." (PMID 32722129, 2020). "More recently, a similar repression of the cyclin D1 expression mediated by a protein-RNA complex was described in Ewing sarcoma cells." (PMID 32183847, 2020). "Of the 4 cases of renal Ewing sarcoma in our series, 3 (75%) demonstrated focal to diffuse staining for Cyclin D1 which was very intense in 2 cases." (PMID 30736802, 2019). "This approach generated a total of 147 genes, containing a number of known Ewing sarcoma oncogenes such as CCND1, NKX2–2, BCL11B and MYC." (PMID 30496486, 2019). "Many of the top ranked super-enhancer associated genes were genes of known relevance in Ewing sarcoma, including caveolin 1 (CAV1), NKX2.2, ID2 and CCND1." (PMID 26337082, 2015). "We also determined that the cyclin D1 gene (CCND1) is regulated by a super-enhancer and confirmed Ewing sarcoma is selectively dependent on CCND1 and CDK4 compared to other cancer cell lines." (PMID 26337082, 2015). "We then examined the individual gene tracks of two of the largest super-enhancers in Ewing sarcoma, which were associated with CAV1/2 and CCND1." (PMID 26337082, 2015). "We next validated the results of our functional genomic screening by analyzing the cyclin D1/CDK4 dependency in Ewing sarcoma in vitro." (PMID 26337082, 2015). "Ewing sarcoma cells were dependent on cyclin D1 for colony formation in methylcellulose, a measurement of anchorage independent growth." (PMID 26337082, 2015).
Ewing sarcoma (continued). "Another mechanism reported to enhance cyclin D1/CDK4 pathway activation in Ewing sarcoma is via the EWS/FLI1 fusion protein binding the CCND1 gene promoter resulting in increased expression of cyclin D1 protein." (PMID 26337082, 2015). "The suppression of EWS/FLI1 also leads to a selective decrease in protein expression of the Ewing sarcoma super-enhancer-associated genes CAV1 and CCND1 versus a vinculin control." (PMID 26337082, 2015). "We show that Ewing sarcoma cells have an activated cyclinD1/CDK4 pathway and are sensitive to both chemical inhibition of CDK4 and shRNA suppression of CDK4 and cyclin D1." (PMID 26337082, 2015). "Earlier studies have shown that Ewing’s sarcoma-specific EWS-ETS oncoproteins were capable of activating Cyclin D1 promoter in transient transfections of tissue culture cells." (PMID 23145994, 2012). "Overexpression of pncCCND1_B in Ewing sarcoma cells led to significant downregulation of the CCND1 transcript, whereas its silencing, although reducing the expression only of 40%, led to a slight but significant increase in CCND1 expression." (PMID 35326688, 2022). "Moreover, we recently reported that Sam68 interacts with pncCCND1_B to repress CCND1 transcription and Cyclin D1 expression in Ewing sarcoma cells." (PMID 35326688, 2022). "Notably, pncCCND1_B overexpression or siRNA-mediated downregulation were sufficient to modulate CCND1 expression in Ewing sarcoma cells." (PMID 35326688, 2022). "Out of the 4 cases of renal Ewing sarcoma, 3 (75%) demonstrated staining for Cyclin D1." (PMID 30736802, 2019). "In our analysis, cyclin D1 is a hit in the combinatorial screening in Ewing sarcoma." (PMID 26337082, 2015). "Particularly, a super-enhancer regulates cyclin D1 and promotes its expression in Ewing sarcoma." (PMID 26337082, 2015). "Toward this end, we integrated the results of super-enhancer profiling, a near-whole genome shRNA screen, and a publically available chemical screening database to identify a dependency of Ewing sarcoma cells on the G1 cell cycle signaling proteins cyclin D1 and CDK4." (PMID 26337082, 2015). "Thus, the regulation of cyclin D1 expression in Ewing sarcoma cells results from the mutually exclusive binding of two different complexes to the CCND1 promoter: one composed by EWS-FLI1 and DHX9, promoting cyclin D1 expression, and a repressive complex formed by Sam68, DHX9, and pncCCND1_B." (PMID 32722129, 2020). "There are several proposed mechanisms by which cyclin D1/CDK4 may be deregulated in Ewing sarcoma." (PMID 26337082, 2015). "On the other hand, mitogenic stimulation of Ewing sarcoma cells by treatment with Insulin-like Growth Factor (IGF)-1 inhibits the interaction between Sam68 and pncCCND1_B and leads to an increase in cyclin D1 transcription." (PMID 32722129, 2020). "Amongst this compendium of cell lines, the expression of CCND1 is highest and the expression of CDK4 is the second highest in the ten Ewing sarcoma cell lines." (PMID 26337082, 2015). "We demonstrated that Ewing sarcoma cells require CDK4 and cyclin D1 for survival and anchorage-independent growth." (PMID 26337082, 2015). "We found that CCND1 and CDK4 were expressed at higher levels in Ewing sarcoma cells compared to other G1 checkpoint transcripts based on RNA sequencing data from primary patient Ewing sarcoma tumors and cell lines." (PMID 26337082, 2015). "Our combination of super-enhancer, functional genomic, and small-molecule screening has converged on the discovery of a dependency on cyclin D1 and CDK4 in Ewing sarcoma." (PMID 26337082, 2015).
Ewing sarcoma (continued). "We used a combination of super-enhancer profiling, near-whole genome shRNA-based and small-molecule screening to identify cyclin D1 and CDK4 as Ewing sarcoma-selective dependencies." (PMID 26337082, 2015). "In particular, high-grade endometrial stromal sarcomas have round blue cell morphology, may have pseudo rosettes and are commonly positive for CD99, Cyclin D1 and KIT, all of which are also positive in Ewing sarcoma." (PMID 39777304, 2024). "For example, in two patients with prolonged stable disease on ribociclib combined with chemotherapy, CCND1 was not overexpressed compared with the total cohort but highly overexpressed with other Ewing sarcomas." (PMID 36182817, 2022). "Ewing sarcoma is a pediatric tumor characterized by chromosomal translocations, giving rise to the oncogene EWS-FLI1, which triggers the transcription of genes involved in neoplastic transformation including CCND1." (PMID 35326688, 2022). "To determine whether CCND1 and CDK4 are more highly expressed in Ewing sarcoma versus other tumors, we compared Ewing cells to other tumor types by using the data generated from the Cancer Cell Line Encyclopedia (CCLE)." (PMID 26337082, 2015). "Notably, cyclin D1, as well as its cell cycle regulatory partner, CDK4, were present in all Ewing sarcoma cell lines tested." (PMID 26337082, 2015). "Similarly, Palombo and colleagues described a cognate pancRNA transcribed from the same region, the pancCCND1_B, expressed in Ewing sarcoma and actively recruiting a multimolecular complex composed by the RNA binding protein Sam68 and the RNA/DNA helicase DHX9 to inhibit CCND1 transcription." (PMID 32183847, 2020). "Thus Cyclin D1 cannot reliably distinguish between CCSK and Ewing sarcoma." (PMID 30736802, 2019). "CCND1 (cyclin D1) has been shown to be overexpressed in PNET and Ewing’s sarcoma, but not in rhabdomyosarcoma." (PMID 32392854, 2020).
liver fibrosis (18 papers, 2016 to 2026). "Hyperplasia of hepatocytes is one of the main causes of liver fibrosis, which is consistent with our observations that the expression level of cyclin D1 is apparently lower in CCl4-treated KLF4-overexpressing mice than in those pretreated with the null plasmid." (PMID 31687083, 2019). "Additionally, paraplastic hepatocytes are one of the main causes of liver fibrosis, and RT-PCR and Western blotting analyses showed that cyclin D1 expression levels were apparently lower in the KLF4-overexpressing mice than in those treated with the null plasmid prior to CCl4 administration." (PMID 31687083, 2019). "We found that low expression of PLK1 by AAV‐shPLK1 significantly decreased the expression of β‐catenin, c‐Myc and Cyclin D1 in CCl4‐induced liver fibrosis mice compared with AAV‐empty mice." (PMID 32463161, 2020). "Another study showed that the mixture of RSM extract and Astragalus Membranaceus extract at a ratio of 1:1 could regulate the expression of TGF-β1 and Cyclin D1 to improve liver fibrosis and the liver functions, especially having a good effect on reducing the cyclin D1 expression." (PMID 34803712, 2021). "Both hBM-MSCs and hBM-MSCs-Ex treatment significantly inhibited the expression of PPARγ, Wnt3a, Wnt10b, β-catenin, WISP1, Cyclin D1, α-SMA, and Collagen I in both HSCs and liver fibrosis tissues (p < 0.005, p < 0.001)." (PMID 30885249, 2019). "The results revealed that quercetin and luteolin could activate the PI3K-Akt signaling pathway and inhibit liver fibrosis by binding to hub targets, including AKT1, CCND1, EGFR, MAPK1, MYC, and RELA." (PMID 37083803, 2023). "In addition, we found that hBM-MSCs-Ex inhibited the expression of Wnt/β-catenin pathway components (PPARγ, Wnt3a, Wnt10b, β-catenin, WISP1, Cyclin D1), α-SMA, and Collagen I, in both HSCs and liver fibrosis tissue." (PMID 30885249, 2019).
meningioma (18 papers, 2008 to 2026). A generally slow growing tumor attached to the dura mater. "In one study, association of the high expression of cyclin D1 with poor RFS of WHO grade II meningioma patients was reported using univariate Cox regression analysis (HR = 2.02, 95%CI 1.298 to 2.742)." (PMID 38758750, 2024). "In a recent study, all grades of meningiomas exhibited Cyclin D1 expression, and Cyclin D1 level which increased at higher grades was linked to poorer prognosis." (PMID 26950155, 2016). "Thus, the synergy we observed between Nf2 and p16Ink4 mutations in meningioma development reflects the concomitant loss of two regulators of CDK4 activity resulting in cyclin D1 activation." (PMID 17924978, 2008). "CONCLUSION: Cellular senescence-associated genes GAPDH, CCND1, and HBEGF show associations with M2 macrophage polarization and inflammatory cytokine secretion in meningioma." (PMID 41840566, 2026). "The tumor cells stained positive for commonly observed meningioma markers like vimentin, reticulin, and cyclin D1." (PMID 39139315, 2024). "CCND1 mRNA was identified as a target of hsa-miR-193b-3p as further validated using luciferase reporter assay in IOMM-Lee meningioma cells." (PMID 37686289, 2023). "Our study indicates an onco-suppressive function of hsa-miR-193b-3p and a direct role of DNA hypermethylation of MIR193B in the increase of cellular proliferation in meningiomas that relates to overexpression of cyclin D1." (PMID 37686289, 2023). "The cyclin D1 protein level was assessed upon immunohistochemical (IHC) staining of meningioma tissue samples (including twenty-three GI, fifteen GII, and two GIII tumors)." (PMID 37686289, 2023). "Our results support using this class of drugs, especially in more aggressive meningiomas, in which cyclin D1/CDK pathway appears activated." (PMID 37686289, 2023). "Accordingly to the observation of lower expression of hsa-miR-193b-3p in GII than in GI meningiomas, we noticed increased cyclin D1 protein levels in atypical as compared to benign tumors." (PMID 37686289, 2023). "Our results on IOMM-Lee meningioma cells confirm that hsa-miR-193b-3p downregulates cyclin D1 levels, and it binds the predicted target site at CCND1 3′UTR." (PMID 37686289, 2023). "Since hsa-miR-193b-3p regulates proliferation of meningioma cells through negative regulation of cyclin D1 expression, it seems to be an important tumor suppressor in meningiomas." (PMID 37686289, 2023). "A similar relationship between cyclin D1 and meningioma grade with a stepwise increase in cyclin D1 expression levels from GI to GIII tumors was also previously reported." (PMID 37686289, 2023). "Considering the influence of hsa-miR-193b-3p on the proliferation of IOMM-Lee cells and expression of CCND1 in meningiomas, we focused on experimental verification of the role of this miRNA in regulation of cyclin D1 levels." (PMID 37686289, 2023). "siRNA targeting of cyclin D1 also diminished meningioma cell invasion via suppression of extracellular matrix metalloproteinases in vitro." (PMID 35936751, 2022). "Accordingly, administration of NSC140905, a small molecule inhibitor of GATA-4 reduced expression of cyclin D1 and diminished meningioma cell viability in vitro." (PMID 35936751, 2022). "It has been reported that cyclin D1 is overexpressed in meningioma, and positively correlated with the degree of malignancy and rate of recurrence in meningioma." (PMID 33042832, 2020). "CCND1 overexpressed and gene amplification is reported in many cancers including the meningioma and pituitary adenomas." (PMID 32373934, 2020). "A separate study showed that an increase in FoxM1 expression can be observed in higher-grade meningioma, promoting the expression of β-catenin and cyclin D1, finally leading to proliferation and colony formation in meningioma cells." (PMID 33042832, 2020).
meningioma (continued). "Knockdown of cyclin D1 expression in the meningioma cell lines IOMM-Lee and CHl57 demonstrated inhibition of the growth and proliferation of the cells." (PMID 33042832, 2020). "Other molecules expression such as Vav3, SPARC, p-Akt, cyclin D1 and Ki-67 were found in meningiomas and correlate with meningioma invasiveness, aggressiveness and recurrence." (PMID 31123490, 2019). "Nuclear Cyclin D1 expression was positive in all studied meningiomas, while its expression in arachnoid was limited to a few trabecular cells." (PMID 26950155, 2016). "Cyclin D1 expression, which is important for G1/S progression, was diminished in meningioma cells as a consequence of Pak inhibitor administration." (PMID 25596744, 2015). "Upregulation of ERK1/2 T202/Y204 and downregulation of STAT3 mediated by AKAP12 may be resulting in the overexpression of CCND1 in high-grade meningiomas." (PMID 29391485, 2018). "In our study, fibroblastic meningioma was detected with increasing expression of CCND1, CDK6, and E2F3, and decreasing expression of CDKs inhibitors including CDKN1A, CDKN2A, and CDKN2B, suggesting a role of cell cycle deregulation in the tumorigenesis of fibroblastic meningioma." (PMID 23285163, 2012). "We next assessed the expression levels of cyclin D1 and p27kip1, which are two proteins involved in the cell cycle, that are modulated by SSAs in neuroendocrine tumors and expressed in meningiomas by western blotting in eight meningioma samples (six WHO grade I and two WHO grade II)." (PMID 28903425, 2017). "Our results demonstrate hyperphosphorylation of RB1 Ser780 and increased CCND1, CDK4, and CDK6 expression in high-grade meningiomas and after AKAP12 knockdown." (PMID 29391485, 2018). "Finally, in vitro gene knockdown experiments were performed to validate the functional roles of GAPDH, CCND1, and HBEGF in meningioma and M2 macrophage polarization." (PMID 41840566, 2026). "This arachnoid sample also had some Cyclin D1 positive cap cells, but it is not clear if this deceased patient was developing meningioma." (PMID 26950155, 2016). "The authors found four genes linked to the Wnt signalling: beta-catenin (CTNNB1), the regulatory subunit of cyclin-dependent kinase 5 (CDK5R1), ectodermal-neural cortex 1 (ENC1) and cyclin D1 (CCND1), with the increased expression in meningiomas examined by microarray." (PMID 27429002, 2016). "Nuclear expression of Cyclin D1 was present as a strong or moderate signal throughout the meningiomas regardless of being grades I or II." (PMID 26950155, 2016). "Cyclin D1 expression assessed by IHC revealed a strong or moderate expression throughout all studied meningiomas regardless of being grades I or II." (PMID 26950155, 2016). "Lower expression of cyclin D1 is observed in atypical rather than in benign meningiomas." (PMID 37686289, 2023). "Low expression of the tumor suppressor RUNX1T1, in concert with the expression of p63 and Cyclin D1 could be contributing factors to the tumor growth in the non-anaplastic meningiomas." (PMID 26950155, 2016).